EEF2K (eukaryotic elongation factor 2 kinase)
Diseases named in the same sentence as EEF2K in open-access papers (continued):
Sharing a sentence is not in itself a finding about the gene and the disease.
tumor (continued). "Overall, the activity of eEF2K is known to change with the conditions of the tumor microenvironment (e.g., energy deficiency, hypoxia, low pH), thereby regulating the process of tumor protein synthesis and ultimately protecting the survival of tumor cells in otherwise harsh conditions." (PMID 33673713, 2021). "Interestingly, both eEF2K and JNK are implicated in autophagy, and eEF2K seems to be particularly important for survival of tumor cells in hypoxic or nutrition-starved conditions." (PMID 25471453, 2014). "In addition, the ability to penetrate tumors and tumor cell–killing functions are impaired in CD8+ T cells deficient in eEF-2K, which could be a consequence of premature exhaustion and senescence of these cells." (PMID 35108044, 2022). "Eukaryotic elongation factor 2 kinase (eEF2K) is highly expressed in TNBC and known to promote tumor progression; however, the precise mechanisms underlying its oncogenic role remain elusive." (PMID 42003905, 2026). "Here, we report that the expression of Eukaryotic Elongation Factor-2 Kinase (eEF2K) is associated with shorter patient survival and demonstrate that eEF2K signaling is critical for the PDAC tumor growth and regulated by the TME." (PMID 40624025, 2025). "Higher eEF2K expression was also observed in tumor tissues of PDAC patients compared to normal tissues." (PMID 40624025, 2025). "In vivo targeting of eEF2K suppressed tumor growth, induced marked apoptosis and reduced the accumulation of TAMs in PDAC tumors, with no observed toxicity." (PMID 40624025, 2025). "eEF2K is overexpressed in cancers and correlates with poor prognosis as it promotes tumor survival under metabolic stress, enhances chemoresistance, and facilitates metastatic progression." (PMID 40567376, 2025). "In summary, while the tumor-promoting role of eEF2K has been reported in several solid cancers, this is the first study demonstrating its multifaceted oncogenic role in promoting tumor growth and progression." (PMID 40624025, 2025). "We found that FOXM1, AXL, and eEF2K are significantly overexpressed in GBM patient tumor samples and FOXM1 regulates the expression of AXL and eEF2K by physically interacting with these proteins." (PMID 40725039, 2025). "In conclusion, our findings reveal for the first time that eEF2K is a critical oncogenic driver of PDAC tumor growth and thus targeting eEF2K represents a promising and novel therapeutic strategy for PDAC." (PMID 40624025, 2025). "To further validate the role of eEF2K in LHA-mediated anti-tumor effects, we established eEF2K-overexpressing PDAC cell lines using lentiviral vectors." (PMID 40567376, 2025). "Acute nutrient deprivation leads to a very robust activation of eEF2K and the subsequent inhibition of translational elongation, an important issue for tumor progression." (PMID 40173236, 2025). "LHA also decreased the expression of eEF2K and increased the expression of pyroptosis markers in the tumor tissues from the PDAC xenograft models." (PMID 40567376, 2025). "Next, we harvested tumor tissues and stained them with eEF2K, GSDMD, and GSDME immunofluorescence markers." (PMID 40567376, 2025). "The inhibition of eEF2K can sensitize cancer cells to apoptosis and suppress tumor growth, positioning it as a promising therapeutic target." (PMID 40567376, 2025). "Growing evidence has shown that eEF2K is activated and overexpressed in many tumors/cancers, promoting cell proliferation, survival, and aggressive tumor characteristics leading to tumor growth and progression." (PMID 39592671, 2024). "In this study, we investigated the expression of eEF2K in different tumor types and its potential role in cancer progression." (PMID 39592671, 2024).
tumor (continued). "Altered gold anti-eEF2K siRNA NPs were very effective as a therapeutic of TNBC tumors in mice xenografts, ensuing knockdown of eEF2K expression and reduction of tumor development and spreading." (PMID 39199788, 2024). "A recent study demonstrated that EEF2K plays a key role in the maintenance of aggressive tumor behavior and chemoresistance in treatment-resistant TNBC." (PMID 38339272, 2024). "Taken together, these results reveal that C1 down‐regulates eEF2K and exerts a potent tumor suppressive effect in vivo." (PMID 38084501, 2024). "In a literature search, we failed to retrieve any publication on pan-cancer analysis of eEF2K from the perspective of the tumor as a whole." (PMID 39592671, 2024). "We demonstrated that miR-34a acts as a tumor suppressor in TNBC by suppressing the FOXM1/eEF2K oncogenic axis." (PMID 39594778, 2024). "YY1BM specifically binds to the transcription factor YY1, blocking its interaction with the androgen receptor (AR) and leading to the downregulation of eukaryotic elongation factor 2 kinase (eEF2K) expression in tumor cells through the AR signaling pathway." (PMID 37444616, 2023). "This miRNA regulates the eukaryotic elongation factor 2 kinase (eEF2K), which promotes the proliferation and invasion of cancer cells, enhances tumor formation, and triggers drug resistance when overexpressed." (PMID 37576994, 2023). "Consistent with this assumption, a growing number of studies have reported that inhibition of eEF2K expression or activity indeed impairs tumor cells proliferation." (PMID 35956836, 2022). "Much fewer CEA-specific eEF-2K KO CAR-T cells were detected in the tumor tissues as compared with control cells." (PMID 35108044, 2022). "miRNA-22 has been shown to be downregulated in TNBC, reducing inhibitory control over the eukaryotic elongation 2 factor kinase (eEF2K), a tumor growth-promoting and chemoresistance-inducing protein." (PMID 35294699, 2022). "While the current studies of eEF2K mainly focused on tumor itself, our results reveal the role of eEF2K in the regulation of tumor microenvironment, especially immune activity." (PMID 35347072, 2022). "eEF2K has been found to be overexpressed in various cancers and promotes tumor progression via multiple mechanisms." (PMID 35347072, 2022). "Our results reveal a critical role of eEF2K in regulating tumor immune microenvironment by controlling PD-L1 expression, and provide a new approach to enhancing cancer immunotherapy by targeting eEF2K." (PMID 35347072, 2022). "IF assays revealed that knockdown of eEF2K decreased PD-1 protein binding intensity to the tumor cell surface." (PMID 35347072, 2022). "Specifically, targeting EEF2K significantly suppressed tumour cell growth by blocking mRNA translation of the cholesterol biosynthesis transcription factor, sterol regulatory element-binding protein (SREBP) 2, and the proteins it regulates." (PMID 35408842, 2022). "EEF2K is well known as a regulator of protein synthesis through inactivating EEF2 to control tumour initiation and growth." (PMID 35184394, 2022). "The impact of eEF-2K expression on the cytocidal activity of CD8+ T cells was further validated by the experiments demonstrating that augmenting eEF-2K in tumor Ag-specific CD8+ T cells enhanced the antitumor efficacy of CTLs and improved their functionality." (PMID 35108044, 2022). "IHC for the proliferation marker (Ki67) revealed fewer proliferative cells in EEF2K knockdown xenograft tumours compared to that in the control samples." (PMID 35184394, 2022). "All the mice receiving an intravenous infusion of WT CEA CD8+ CAR-T cells survived at least 28 days after tumor induction, whereas the survival of the mice treated with eEF-2K KO CAR-T cells declined rapidly from day 15 onward." (PMID 35108044, 2022). "The regulatory role of eEF2K in PD-L1 expression suggests that eEF2K is involved in modulating immune escape in tumor cells." (PMID 35347072, 2022).
tumor (continued). "As a negative regulator of protein synthesis, eukaryotic elongation factor-2 kinase (eEF-2 K) is observed highly expressed in various tumor cells and proved to exert a critical function in modulating autophagy and apoptosis in tumor cells." (PMID 36209102, 2022). "Circ-ZEB1 knockdown has been shown to reduce TNBC cell proliferation and tumor formation by releasing miR-448 and consequently decreasing the expression of the miR-448 target, eEF2K." (PMID 35865469, 2022). "Tumour growth was measured on alternate days, showing that knockdown of EEF2K reduced the tumour growth by up to 65%, in a manner similar to cells in which BRAF had been targeted and compared to the siScramble control (p < 0.0001)." (PMID 35408842, 2022). "1-Benzyl-3-cetyl-2-methylimidazolium iodide (NH125) is one of the earliest reported eEF2K inhibitors and it has potent anti-proliferative effects against different tumor cells." (PMID 35956836, 2022). "IF staining of the tumor tissues demonstrated that the expressions of PD-L1 and phospho-GSK3β/S9 were decreased when eEF2K was knocked down, supporting that eEF2K modulated T cell activity by regulating PD-L1 expression in mouse model." (PMID 35347072, 2022). "We have also reported that eEF-2K plays a crucial role in regulating autophagy and cellular adenosine triphosphate (ATP) in tumor cells, and in promoting the Warburg effect." (PMID 35108044, 2022). "TUNEL assay indicated significantly increased number of apoptotic cells in EEF2K knockdown xenograft tumours." (PMID 35184394, 2022). "Specifically, we documented significant downregulation of the eukaryotic elongation factor-2 kinase (eEF2K) protein in tumors with marked anti-tumor efficacy." (PMID 35954481, 2022). "AMPK activation promotes tumor cell survival by inhibiting the interaction between eEF2K and mitogen-activated protein kinase (MEK1/2) under nutrient deprivation." (PMID 34532346, 2021). "Of further importance to the field, we also demonstrate in our tumour model that the translation defect in Rpl24Bst mutant mice is restored to normal levels following inactivation of eEF2K in Rpl24Bst mutant mice, showing that the defect is dependent on eEF2K." (PMID 34895463, 2021). "Inhibiting eEF2K decreases the invasion and migration of tumor cells, while deletion of eEF2 or eEF2K overexpression promotes wound healing and invasion." (PMID 35127825, 2021). "Combination of resveratrol and sorafenib have synergetic effect in reducing the PKA/AMPK/eEF2K pathway and inhibiting the tumor in vivo." (PMID 34776832, 2021). "Some eEF2K inhibitors have been shown to induce tumor cell apoptosis by these mediated extrinsic and/or intrinsic apoptosis pathways." (PMID 33673713, 2021). "eEF2K is an atypical kinase, and plays an important role in the migration and survival of tumor cells." (PMID 35127825, 2021). "eEF2K has a pleiotropic effect in tumorigenesis, acting akin to a tumour suppressor or promoter dependent on the context." (PMID 34895463, 2021). "For example, under nutrient deprivation eEF2K acts as a pro-survival factor in transformed fibroblasts and tumour cell lines by suppressing protein synthesis to ensure survival." (PMID 34895463, 2021). "A continually increasing number of studies have shown that eEF2K is related to the occurrence and development of a variety of tumors, and is considered a potential target for tumor chemotherapy." (PMID 33673713, 2021). "We provide genetic evidence supported by molecular assays of translation elongation to demonstrate that RPL24 depletion activates eEF2K to elicit tumour suppression in our models." (PMID 34895463, 2021). "Nevertheless, a recent study showed that eEF2K can protect cells under stress conditions and make tumor cells adapt to stresses." (PMID 35127825, 2021). "Further adaptation of the tumor cells, including by increasing expression of eEF2K, helps to regulate the synthesis of proteins in the harsh environment and be protected for continued proliferation." (PMID 33673713, 2021).
tumor (continued). "Under conditions of nutritional deprivation, tumor cells with high eEF2K expression can continue to survive, while those with low eEF2K expression have been shown to die." (PMID 33673713, 2021). "IHC analyses of tumor tissues showed that eEF2K depletion increased the expression of proliferating cell nuclear antigen (PCNA), a marker of cell proliferation." (PMID 32054489, 2020). "eEF2K was required for all nelfinavir-mediated anti-tumour activity, indicating suppression of elongation to be the drug's mechanism of action." (PMID 32298235, 2020). "Correspondingly, eEF2K has tumor-suppressive functions in CRC, as depletion of eEF2K enhances cell survival in CRC and low expression levels of eEF2K in CRC patient tissue samples correlate with poor clinical outcome." (PMID 32455578, 2020). "As a vital part, eEF-2K is activated in response to various environmental or metabolic stresses to promote tumor cell survival." (PMID 33144562, 2020). "The important role of eEF-2K in mediating the resistance of tumor cells to mTOR inhibitors enlightens us that the development of effective inhibitors targeting eEF-2K has a good application prospect and can provide a new strategy for tumor treatment." (PMID 33144562, 2020). "At protein level, consistent with the mRNA analysis, EEF2K was significantly reduced in 75% of the cases (15 out of 20) in primary tumor tissue relative to the paired non-tumor tissues." (PMID 31266475, 2019). "Univariate Cox regression analysis revealed that CRC patients with high tumor grade, advanced TNM staging and low EEF2K expression were associated with worse overall survival." (PMID 31266475, 2019). "In our recent study, a tumor-suppressive role of EEF2K was observed in CRC, where silencing of EEF2K induced a pro-survival autophagic response through the AMPK-ULK pathway and promoted CRC growth through increasing cell size, viability and clonogenicity." (PMID 31266475, 2019). "Eighty-five percent of the cases (17 out of 20) showed a more than two-fold downregulation of EEF2K mRNA in cancerous tissues as compared to the adjacent non-tumor tissues." (PMID 31266475, 2019). "Eukaryotic elongation factor-2 kinase (eEF-2K) is a negative regulator of protein synthesis that plays an important role in autophagy and pyroptosis of tumor cells under various conditions." (PMID 31501419, 2019). "Alternatively, eEF2K regulates autophagy implicated in AMPK, mTORC1, and ULK1, thus promoting tumor cell survival." (PMID 30791936, 2019). "In summary, these findings suggest that Fluoxetine effectively inhibits tumor growth of TNBC via promoting apoptosis and autophagy associated with suppression of eEF2K and activation of the AMPK-mTOR-ULK signaling pathway." (PMID 30791936, 2019). "Our previous work demonstrated that eukaryotic elongation factor-2 kinase (EEF2K) is a tumor suppressor in CRC." (PMID 31266475, 2019). "Quantitative RT-PCR and Westerns blots were used to examine EEF2K expression in primary tumor and the adjacent non-tumor tissues of CRC patients (n = 20)." (PMID 31266475, 2019). "For instance, it has been shown that disruption of eEF2K mitigates the antineoplastic effects of mTORC1 inhibition, suggesting tumor-suppressive properties of eEF2K." (PMID 29610153, 2018). "eEF2K is activated under conditions of stress, such as energy depletion or nutrient deprivation, which can arise in poorly-vascularised tumours." (PMID 29186827, 2017). "In this study, we report for the first time that miR-603 acts as a tumor suppressor in TNBC by directly regulating eEF2K expression, thereby inhibiting cell proliferation, survival, invasion, and tumorigenesis." (PMID 28036267, 2017). "We also demonstrated that eEF2K is highly overexpressed in TNBC cells and reduced or loss of miR-603 expression contributes to upregulation of eEF2K and TNBC tumor growth and progression." (PMID 28036267, 2017).
tumor (continued). "Tumor samples were further analyzed by western blotting for the expression of eEF2K and the downstream targets of eEF2K, including p-EF2, p-Src, p-Akt, p-Fak, and c-myc." (PMID 28036267, 2017). "Further studies are needed to define the role of eEF2K in different tumour types and at differing stages in tumorigenesis, and to assess its utility as a therapeutic target in oncology." (PMID 29186827, 2017). "Loss of eEF2K reduced the growth of RasV12-transformed NIH3T3 xenografts under caloric restriction, again, indicating that eEF2K protects tumours against caloric-restriction induced cell death in vivo." (PMID 29186827, 2017). "Therapeutic inhibition of eEF2K prevents tumor growth and enhances the efficacy of chemotherapy in pre-clinical TNBC models in mice, indicating that eEF2K is an important regulator of tumor growth and progression and a potential therapeutic target in TNBC." (PMID 26918606, 2016). "In our study FOXM1-B and -1-C had similar effects on eEF2K expression and cell proliferation, migration, invasion and in vivo tumor growth in TNBC model." (PMID 26918606, 2016). "We also found that miR-21-3p reduced the expression of EEF2K, which has been reported as a valid target for anti-cancer treatment because it allows tumor growth and resists cell death." (PMID 24098708, 2013). "Given the pronounced growth inhibitory effects of down-regulating eEF-2K, the tumor samples were examined for evidence of the induction of apoptosis." (PMID 22911754, 2012). "In TNBCs, eEF2 K is overexpressed, contributing to tumor progression and poor prognosis." (PMID 40266550, 2026). "Notably, in vivo targeting of the eEF2K/MCP-1 signaling axis with siRNA-nanotherapeutics inhibits tumor growth, induces apoptosis, and reduces the accumulation of pro-tumorigenic M2-TAMs in orthotopic mouse models of PDAC." (PMID 40624025, 2025). "Additionally, eEF2K enhances the expression of integrins by promoting the association of their mRNAs with polysomes, suggesting further mechanisms by which eEF2K promotes tumor growth." (PMID 40624025, 2025). "Western blot analysis confirmed eEF2K overexpression in tumor xenografts from these mice." (PMID 40624025, 2025). "Notably, in vivo silencing of eEF2K in PDAC mouse tumor xenografts inhibited tumor growth, decreased MCP-1 expression, and reduced TAM accumulation." (PMID 40624025, 2025). "Since activation of the DDR acts as a barrier against tumorigenesis, eEF2K activation of DDR pathways could support a tumor suppressive function of eEF2K." (PMID 39003251, 2024). "Given the clinical relevance of eEF2K in promoting cancer cell survival and tumour development, and the use of cisplatin as a chemotherapeutic agent for multiple tumour types, we sought to clarify the relationship between the molecular functions of eEF2K and cisplatin-induced DNA damage." (PMID 39003251, 2024). "This may be related to its role in regulating protein synthesis and other cellular processes, but is also influenced by several factors, including the specific cancer cell type, the tumor microenvironment, and the activation level of eEF2K." (PMID 39592671, 2024). "However, the role of eEF2K in cancer is still being scrutinized, as eEF2K displays both pro-tumorigenic and tumor suppressive functions depending on the tumor entities and the type of stress." (PMID 39003251, 2024). "Furthermore, we assessed the relationship between the anti‐cancer activity and eEF2K expression in tumor cells treated with C1." (PMID 38084501, 2024). "The administration of nanoparticles containing the tumor-suppressor micro-RNA miR-603 to TNBC-cell-xenografted mice inhibited the expression of eEF-2K and the activity of downstream signaling systems, including c-Src, inhibiting tumor cell growth, cell migration, and invasiveness." (PMID 38136610, 2023).